PRRX1 (paired related homeobox 1)
Diseases named in the same sentence as PRRX1 in open-access papers (continued):
Sharing a sentence is not in itself a finding about the gene and the disease.
triple-negative breast carcinoma (4 papers, 2018 to 2025). An invasive breast carcinoma which is negative for expression of estrogen receptor (ER), progesterone receptor (PR), and human epidermal growth factor receptor 2 (HER2). "C James Block found that RBMS3 bound to and stabilized the mRNA of PRRX1, which in turn promoted the development of triple-negative breast cancers." (PMID 40155591, 2025). "Zhi-Dong Lv, Bin Kong, Xiang-Ping Liu, Li-Ying Jin, Qian Dong, Fu-Nian Li, Hai-Bo Wang, miR-655 suppresses epithelial-to-mesenchymal transition by targeting Prrx1 in triple-negative breast cancer." (PMID 38655709, 2024). "In triple-negative breast cancer, the expression of PRRX1 is downregulated by miR-655, which consequently suppresses the occurrence of EMT43." (PMID 32811812, 2020).
esophageal cancer (3 papers, 2018 to 2024). A primary or metastatic malignant neoplasm involving the esophagus. "In the colon, stomach, and esophageal cancers, patients with PRRX1 protein expression in CAFs showed unfavorable prognosis." (PMID 35589735, 2022).
leukemia (3 papers, 2021 to 2025). A malignant (clonal) hematologic disorder, involving hematopoietic stem cells and characterized by the presence of primitive or atypical myeloid or lymphoid cells in the bone marrow and the blood. "A recent study by Golovine et al47 has highlighted the significant role of ABL1 kinase in AML1-ETO and NUP98 (nucleoporin 98)-PMX1 (paired related homeobox 1) leukemias." (PMID 40584293, 2025).
sarcoma (3 papers, 2019 to 2024). A usually aggressive malignant neoplasm of the soft tissue or bone. "We collected human sarcoma tissue samples for immunohistochemical analysis and found that these sarcomas expressed PRRX1." (PMID 38448751, 2024). "In summary, we report the generation of multiple conditional mouse models of FUS-CHOP-driven sarcoma and show that Prrx1-expressing cells are a potential source of myxoid liposarcoma." (PMID 31427882, 2019). "Indeed, PRRX1 was highly expressed in CAFs of various sarcomas and less so in benign tumours such as schwannoma and neurofibroma." (PMID 38448751, 2024). "In this study, we showed that PRRX1 was highly expressed in various types of human sarcoma tissues and might contribute to malignancy in MPNST patients by enhancing cell motility." (PMID 38448751, 2024). "Notably, sarcoma tissues expressed a significantly higher level of PRRX1 than normal or other tumour tissues." (PMID 38448751, 2024).
stomach adenocarcinoma (3 papers, 2016 to 2025). "Moreover, pathogenic mutations and low expression of PRRX1 in stomach adenocarcinomas (STADs) are linked to genomic instability and defective NHEJ." (PMID 40114375, 2025).
type II diabetes (3 papers, 2021 to 2022). "In a recent genome-wide association study linking type II diabetes sensitivity with gene expression patterns, the authors showed that PRRX1 is positively linked with insulin sensitivity, supporting the finding that PRRX1 is related to glucose metabolism." (PMID 34496784, 2021). "PRRX1 can play a role on lipid metabolism and induce the release of free fatty acids (FFAs), promoting the development of type II diabetes." (PMID 35032368, 2022). "Moreover, PRRX1 is known to induce the accumulation of fatty acid and insulin resistance in type 2 diabetes." (PMID 35032368, 2022).
colon cancer (2 papers, 2021 to 2022). "PRRX1 has been found to be overexpressed in breast, pancreas, head and neck squamous cell carcinoma, liver, and colon cancer." (PMID 34496784, 2021). "In other studies, knockdown of PRRX1 reduced tumour volume of MDA-MB-231 mice xenografts, and its overexpression in colon cancer cell lines increased colony formation and anchorage independent growth." (PMID 34496784, 2021).
coronary artery diseases (2 papers, 2024 to 2025). "In perspective, inhibition of Prrx1 S-nitrosylation is an effective approach to improve cardiac remodeling in patients with ischemic heart diseases." (PMID 41168006, 2025). "This novel mechanism not only uncovers a molecular mechanism by which Prrx1 is activated in cardiac fibroblasts, but also provides a novel target for exploring new drugs to improve the prognosis of ischemic heart disease." (PMID 41168006, 2025).
fibrosis (2 papers, 2025). the formation of excess fibrous connective tissue in an organ or tissue in a reparative or reactive process. "To exclude the contributions of other cells in Prrx1-mediaeted cardiac fibrosis, we generated fibroblast-specific Prrx1 gene knockout (Prrx1FB−/-) mice by crossing Prrx1flox/flox mice with Col1a2-iCreER mice followed by MI surgery for 4 weeks." (PMID 41168006, 2025).
Insulin resistance (2 papers, 2020 to 2022). Increased resistance towards insulin, that is, diminished effectiveness of insulin in reducing blood glucose levels. "In conclusion, we identified the homeobox factor PRRX1 as a novel transcriptional regulator associated with COL6A3 expression, providing new insight into the regulatory mechanisms of altered adipose tissue function in obesity and insulin resistance." (PMID 33214660, 2020).
osteoarthritis (2 papers, 2019 to 2024). A noninflammatory degenerative joint disease occurring chiefly in older persons, characterized by degeneration of the articular cartilage, hypertrophy of bone at the margins and changes in the synovial membrane. "Only the Prrx1-lineage cells isolated from white adipose tissues showed long-term therapeutic effectiveness on early-stage osteoarthritis models." (PMID 38561335, 2024). "(F) Quantitative PCR analysis of articular cartilage samples of Prrx1-CreERT; Ptch1f/f and control mice revealed alteration of gene expression that indicated osteoarthritis phenotypes." (PMID 31482846, 2019). "Histological analyses revealed that Prrx1-CreERT; Ptch1f/f mice exhibited signs of osteoarthritis with high OARSI scores at 2.5 months of age (2 months after TAM injection), and increased fibrotic cells lining the damaged cartilage surfaces, which were positive for fibrosis marker FSP1." (PMID 31482846, 2019).
otocephaly (2 papers, 2020 to 2025). "At least four otocephaly cases are known to be caused by a mutation in the gene PRRX1 on the long arm of chromosome 1." (PMID 40709982, 2025). "While the knowledge on the causes of otocephaly in animals is limited, different syndromic forms in man are associated with variants of the PRRX1 and OTX2 genes." (PMID 31969185, 2020).
renal carcinoma (2 papers, 2021). A carcinoma arising from the epithelium of the renal parenchyma or the renal pelvis. "Moreover, high expression of PRRX1 was associated with lower survival in renal cancer." (PMID 34608135, 2021). "On a similar note, a significant association between the expression of ELK4, CBFB, IFI16, PRRX1, AEBP1, and GATA3 with an unfavourable outcome in renal cancer has been identified in previous reports." (PMID 35201514, 2021). "For instance, ELK4, CBFB, IFI16, PRRX1, AEBP1, and GATA3 expression was associated with an unfavourable outcome in renal cancer revealing the significance of these TFs (pink and blue colours represent unfavourable and favourable prognosis, respectively)." (PMID 35201514, 2021).
skin cutaneous melanomas (2 papers, 2022). "Overexpression of PRRX1 was found to promote migration, invasion, and tumorigenesis and induce EMT in skin melanoma." (PMID 35281030, 2022). "In addition, in 469 samples of skin cutaneous melanomas from the TCGA, a positive correlation was found for LOXL3 gene expression with both SNAI1 and PRRX1 expression (R = 0.4 and R = 0.45, respectively), as well as for PRRX1 with SNAI1 expression (R = 0.45)." (PMID 35267510, 2022).
adenoid cystic carcinoma (1 paper, 2020). A malignant tumor arising from the epithelial cells. "Collectively, these results suggest that PPARG2 plays a critical role in the regulation of PRRX1‐induced invasion and migration of salivary adenoid cystic cancer cells in response to FFAs." (PMID 31657086, 2020).
Apert syndrome (1 paper, 2018). Apert syndrome (AS) is a frequent form of acrocephalosyndactyly, a group of inherited congenital malformation disorders, characterized by craniosynostosis, midface hypoplasia, and finger and toe anomalies and/or syndactyly. "Limb defects in Pfeiffer and Apert syndromes are similar to those in Tg(Prrx1-EGFP-Runx2) mice with low expression levels." (PMID 30202094, 2018).
Arrhythmia (1 paper, 2023). Any cardiac rhythm other than the normal sinus rhythm. "This is consistent with the observed longer atrial APD in Tbx5RE(int)KO mice compared to controls, which may predispose to increased arrhythmia inducibility, as seen in mice harboring the pathogenic TBX5-G125R variant or Prrx1 enhancer deletion." (PMID 36715501, 2023).
benign salivary gland tumor (1 paper, 2022). "In the present study, the results of RT‐qPCR showed PRRX1 was significantly enhanced, while LC3B and BECLIN 1 were declined in SACC tissues compared with normal tissues (NT) of the periphery of benign salivary gland tumor." (PMID 35032368, 2022).
bone tumors (1 paper, 2019). "Ptch1 deficiency-induced cartilage/bone tumors were originated from Prrx1 lineage cells." (PMID 31482846, 2019). "(F) Western blot showed an increase in Gli1 in bone tumor tissues isolated from Prrx1-CreERT; Ptch1f/f mice compared to normal periosteal cells." (PMID 31482846, 2019). "The cartilage and bone tumors are originated from Prrx1+ lineage cells and express low levels of osteoblast and chondrocyte markers, respectively." (PMID 31482846, 2019). "(G) H/E-staining showed that IWP2 rescued bone tumor formation in Prrx1-CreERT; Ptch1f/f mouse." (PMID 31482846, 2019). "The Prrx1-CreERT; Ptch1f/f mouse line is one of the few models for cartilage/bone tumors." (PMID 31482846, 2019). "(C) Radiographic images of bone tumors in Prrx1-CreERT; Ptch1f/f mice 5 months after TAM injection." (PMID 31482846, 2019).
brain tumor (1 paper, 2022). "Using the public database TCGA, we analyzed the expression of genes studied in the present study, including PRRX1, PROM1, and DNMT3A, to investigate possible correlations between the expression of these genes, the brain tumor grade, and patient prognosis." (PMID 34214250, 2022).
breast tumors (1 paper, 2018). "Quantitative data confirmed a strong positive correlation between endogenous SIRT1 and PRRX1 levels in breast tumors (R = 0.867, P = 0.001)." (PMID 30038266, 2018).
cervical cancer (1 paper, 2025). A primary or metastatic malignant neoplasm involving the cervix. "Accumulation of LDs promoted EMT and the subsequent lymph node metastasis in cervical cancer while paired related homeobox 1 (PRRX1) ‐induced EMT activated the reprogramming of FAs metabolism contributing to the enhanced invasion and metastasis in salivary adenoid cystic carcinoma." (PMID 39875372, 2025).
fibrous dysplasia (1 paper, 2018). A genetic, non-inheritable disorder caused by osteoblastic differentiation defects that result in the replacement of bone marrow and trabecular bone by fibrous stroma and immature bone. "Similar to what has been reported in CT scans of human polyostotic fibrous dysplasia, the Prrx1-Cre; Gnasf(R201H)/+ mutant skull showed mixed-density fibrous dysplasia lesions with mixed lucencies and sclerosis." (PMID 30479847, 2018).
Intellectual disability (1 paper, 2020). "PRRX1 is associated with intellectual disability and delayed language acquisition." (PMID 36794006, 2020).
ischemia (1 paper, 2025). A hypoperfusion of the BLOOD through an organ or tissue caused by a PATHOLOGIC CONSTRICTION or obstruction of its BLOOD VESSELS, or an absence of BLOOD CIRCULATION. "When MI happens, due to ischemia, Prrx1 is activated by TGF-β through S-nitrosylation to enhance Wnt5a signaling, which induces FMD." (PMID 41168006, 2025).
keratoacanthoma (1 paper, 2019). A dome-shaped, rapidly growing skin lesion composed of well differentiated squamous cells. "Due to the formation of keratoacanthomas and to spatially restrict generation of tumors, we crossed Rosa26 LSL-FUS-CHOP/+ mice with Prrx1-CreER-GFP mice to allow site-specific tumor generation via activation of CreER by intramuscular 4-OHT." (PMID 31427882, 2019). "Prrx1-Cre; Rosa26 FUS-CHOP/+ mice developed keratoacanthomas shortly after birth." (PMID 31427882, 2019).
knee osteoarthritis (1 paper, 2024). "Here we used knee osteoarthritis mouse model to assess the therapeutic effects of MSCs isolated from the white adipose or dermal adipose tissue of Prrx1-Cre; R26tdTomato mice and Dermo1-Cre; R26tdTomato mice." (PMID 38561335, 2024).
lung squamous cell carcinoma (1 paper, 2019). "In breast and in lung squamous cell carcinoma patients, high expression of SNAIL1 in tumors correlate with poor prognosis, while high PRRX1 correlates with good prognosis." (PMID 31712603, 2019).
Malignant peripheral nerve sheath tumours (1 paper, 2024). "PRRX1 expression in human Malignant peripheral nerve sheath tumours (MPNSTs) samples was detected immunohistochemically to evaluate survival prognosis." (PMID 38448751, 2024).
mesenchymal neoplasms (1 paper, 2026). "Postoperative pathology, immunohistochemistry, and targeted RNA sequencing identified a PRRX1::KMT2D fusion mesenchymal neoplasm." (PMID 41795606, 2026).
microstomia (1 paper, 2022). "Notably, heterozygous loss-of-function variations in PRRX1 have already been described in patients with agnathia-otocephaly complex, a rare condition characterized by mandibular hypoplasia or agnathia, ear anomalies (melotia/synotia) and microstomia with aglossia." (PMID 35377386, 2022).
Myocardial fibrosis (1 paper, 2025). "To this point, we infected mice with AAV9 expressing Prrx1-WT or Prrx1-MT (C209R), which is S-nitrosylation resistant to NO modification, and detected myocardial fibrosis using Masson staining at the 28th postoperative day." (PMID 41168006, 2025).
neurofibroma (1 paper, 2024). An intraneural or extraneural neoplasm arising from nerve tissues and neural sheaths. "Interestingly, the expression of PRRX1 in MPNST was higher than that in schwannoma or neurofibroma at both the protein and RNA levels." (PMID 38448751, 2024).
Obesity (1 paper, 2020). Accumulation of substantial excess body fat. "Also the omental samples (available from the 12 patients with obesity) showed positive correlations of PRRX1 and COL6A3 mRNA (SVF: p = 8.66E-5, r = 0.894; adipocytes: p = 0.263, r = 0.335, data now shown)." (PMID 33214660, 2020).
Osteochondroma (1 paper, 2018). A common, benign cartiliginous neoplasm arising from the metaphysis of bone. "Second, while palovarotene reduced severity of whole-body HO and inhibited osteochondroma formation in Pdgfrα-R206H mice, palovarotene treatment of Acvr1[R206H]FlEx/+;Prrx1-Cre mice resulted in more marked reductions in HO." (PMID 30226468, 2018).
ovarian carcinoma (1 paper, 2022). A malignant neoplasm originating from the surface ovarian epithelium. "In ovarian cancer, PRRX1 enhances tumor progression and resistance to chemotherapy and radiotherapy by activating COL11A1, and miR-335 inhibits the invasion and migration of ovarian cancer cells by inhibiting the expression of COL11A1." (PMID 36160004, 2022).
ovarian tumors (1 paper, 2018). "To further validate their possible contribution to OC mesenchymal subtype, we found that both CXCR7 and CXCL11 strongly correlate with genes associated with ECM and OC invasion, such as PRRX1, TMEM45A, and CTSK, when analyzed in the mesenchymal counterpart of ovarian tumors." (PMID 30051594, 2018).
pancreatic ductal adenocarcinoma (1 paper, 2022). An infiltrating adenocarcinoma that arises from the epithelial cells of the pancreas. "For instance, PRRX1 isoforms were shown to be important in pancreatic ductal adenocarcinomas (PDAC), especially in the regulation of the EMT and the mesenchymal-to-epithelial transition (MET) in liver metastases of PDAC." (PMID 35281030, 2022). "For example, PRRX1-mediated cancer-associated fibroblast (CAF) plasticity was found to have a significant impact on the biology and resistance to therapy of pancreatic ductal adenocarcinoma." (PMID 35281030, 2022).
pancreatitis (1 paper, 2019). Inflammation of the pancreas. "In the pancreas, Prrx1+ cells were more efficient in sphere formation and, when animals were subjected to caerulein-induced pancreatitis, increased numbers of Prrx1+ cells were found, and the Prrx1b isoform specifically drove Sox9 expression." (PMID 31398893, 2019).
papilloma (1 paper, 2015). A benign epithelial neoplasm that projects above the surrounding epithelial surface and consists of villous or arborescent outgrowths of fibrovascular stroma. "We validated by qRT-PCR the upregulation of EMT drivers, such as Zeb1, Zeb2, Twist and Prrx1, and EMT mediators, such as Wnt5a, Vcan, Ncadh and Mmp2 both in Nanog-papillomas and in Nanog-SCCs." (PMID 25988972, 2015). "In particular, Nanog-overexpressing papillomas show upregulation of several EMT mediators (Zeb1, Zeb2, Twist) and the master EMT inducer Prrx1, but not of the classical EMT inducers Snail/Slug." (PMID 25988972, 2015).
rectal cancer (1 paper, 2022). A primary or metastatic malignant neoplasm that affects the rectum. "The results of UALCAN analysis showed that the expression levels of both IL1RN and PRRX1 were significantly higher in colon and rectal cancer samples than in healthy samples." (PMID 36483329, 2022).
squamous cell carcinoma (1 paper, 2020). A carcinoma arising from squamous epithelial cells. "In squamous cell carcinoma, PRRX1 expression is evidently negatively correlated with miR-642b-3p, which is downregulated in PRRX1-overexpressed cells." (PMID 32811812, 2020).
ulcerative colitis (1 paper, 2022). An inflammatory bowel disease involving the mucosal surface of the large intestine and rectum. "PRRX1 expression in the mucosal tissues of patients with ulcerative colitis was analyzed using the GSE87466 microarray." (PMID 34967278, 2022).
virus infection (1 paper, 2024). "After virus infection and puromycin screening of RM cells, increased and reduced expression profiles of miR-140-3p and Prrx1 were obtained." (PMID 38643083, 2024).